MLANA (melan-A)
Diseases named in the same sentence as MLANA in open-access papers (continued):
Sharing a sentence is not in itself a finding about the gene and the disease.
hemorrhage (1 paper, 2024). Loss of blood from the vascular compartment to the exterior or into nonvascular body space as a result of rupture or severance of the blood vessels. "The presence of hemorrhage and its correlation with Melan-A might suggest an incidental or secondary association rather than a direct causative relationship." (PMID 39399171, 2024). "The only notable exception of a correlation between dermoscopy observed is hemorrhage and the Melan-A marker." (PMID 39399171, 2024).
Kaposi's sarcoma (1 paper, 2011). A malignant neoplasm characterized by a vascular proliferation which usually contains blunt endothelial cells. "The latency genes K-cyclin and LANA, homologs of MHV68 v-cyclin and mLANA, are expressed in all KSHV-associated maglinancies, Kaposi's sarcomas (KS), primary effusion lymphomas (PEL) and multicentric Castleman's diseases (MCD)." (PMID 21931547, 2011).
lung carcinoma (1 paper, 2023). "PBMCs from 26 lung cancer patients were stimulated for 21–28 days with PDC*line cells loaded separately with the 14 selected tumor peptides plus Melan-A." (PMID 36768214, 2023).
lymph node metastasis (1 paper, 2013). "For example melan A combined with DNA content identified a diploid melanocyte population in a lymph node metastasis sample whose genome contained a series of aberrations including homozygous deletion at 9p21.3." (PMID 23372550, 2013).
melanocytic nevus (1 paper, 2023). A neoplasm composed of melanocytes that usually appears as a dark spot on the skin. "The complete regression of the pre-existing melanocytic nevus was confirmed with Melan-A immunostaining." (PMID 37763236, 2023).
melanosis (1 paper, 2020). "In addition, the proliferation of Melan-A-positive melanocytes was also observed in the lesional skin of Riehl’s melanosis." (PMID 32121626, 2020).
neuroendocrine tumor (1 paper, 2015). "Immunohistochemical analysis reported positivity to inhibin alpha and Melan-A (MART-1) and neuron specific enolase and synaptophysin and negativity to PS100 and chromogranin A, which confirmed the diagnosis of a neuroendocrine tumor." (PMID 26161274, 2015).
ocular albinism (1 paper, 2016). Albinism affecting the eye in which pigment of the hair and skin is normal or only slightly diluted. "Thus far, the mechanisms regulating the separation of the melanosomal and endosomal pathway are still elusive but likely involve several actors such as OA1 (ocular albinism) and MART1 (Melan-A)." (PMID 27589732, 2016).
oncocytic neoplasm (1 paper, 2012). A usually benign neoplasm composed of large cells with abundant eosinophilic granular cytoplasm. "Supporting that our present case of an oncocytic neoplasm is of an adrenocortical origin is the strong immunohistochemical staining for inhibin and Melan-A." (PMID 23094172, 2012).
Paget disease (1 paper, 2015). A malignant neoplasm composed of large cells with large nuclei, prominent nucleoli, and abundant pale cytoplasm (Paget cells). "Immunohistochemistry revealed positivity for cytokeratins (CK7 and CK8/18) and negativity for S100 protein and Melan A. Taken together with the morphological features, these findings permitted a diagnosis of Paget disease to be made." (PMID 26060586, 2015).
papilloma (1 paper, 2021). A benign epithelial neoplasm that projects above the surrounding epithelial surface and consists of villous or arborescent outgrowths of fibrovascular stroma. "Our results show high expression of MLANA in papillomas as well as in the epidermis and the dermis of LRIG1‐TG animals and only low expression in control skin." (PMID 33786987, 2021).
prostatic adenocarcinoma (1 paper, 2025). "PanCk and PSA negativity rule out prostatic adenocarcinoma, and Melan A negativity exclude out melanocytic tumors." (PMID 40686513, 2025).
renal angiomyolipoma (1 paper, 2021). "Among the genes upregulated in the TSC2−/− organoids were: MLANA, PMEL, GPNMB, CTSK, and ACTA2, with median expression fold change 121x-, 88x-, 34x-, 14x-, 9.5x, respectively, all of which are known to be highly expressed in the renal angiomyolipoma." (PMID 34764250, 2021).
spindle cell neoplasm (1 paper, 2025). A benign or malignant neoplasm characterized by the presence of neoplastic spindle cells. "Importantly, these tumors are negative for markers such as SMA, Desmin, EMA, Melan-A, and CD34, which aids in ruling out other spindle cell neoplasms." (PMID 41199828, 2025).
Spitz nevi (1 paper, 2025). "Spitz nevi demonstrate strong S100 and Melan A positivity while lacking ALK rearrangement." (PMID 40688914, 2025).
testicular tumours (1 paper, 2011). "Due to the good differentiation of both testicular tumours, immunohistochemistry was only performed for vimentin, CK and Melan A. Histological appearance of most testicular tumours in dogs is highly specific and immunophenotyping of the neoplasia is not necessary." (PMID 21255434, 2011).
thyroid neoplasms (1 paper, 2013). "Melan-A, inhibin, and some other markers have been found to be positive in patients with ACC, and thyroglobulin and TTF-1 have been found to be positive in patients with thyroid neoplasms in immunohistochemical studies." (PMID 23889916, 2013).
Wilms tumor (1 paper, 2021). An embryonal neoplasm characterized by the presence of epithelial, mesenchymal, and blastema components. "In addition, immunohistochemical staining was performed on Sertoli cells for Wilms' Tumor, Melan-A, and CD99 to evaluate histopathological changes." (PMID 34567182, 2021).
tumor (338 papers, 2003 to 2025). "An early and staggering example of TCR cross-reactivity was described by the group of P. Romero for the tumour-associated antigen (TAA) Melan-A." (PMID 37409132, 2023). "We first proved the technical feasibility of this strategy in our hands using HLA-A*0201 tetramers loaded with the Melan-A tumor-associated antigen ELAGIGILTV (pELA/A2)." (PMID 32038634, 2019). "Secondly, EVs isolated from the biofluids of cancer patients or tumour-bearing animals were shown to contain cancer-associated markers, such as Melan-A, TYRP2 and CA19-9, and amplified or mutated oncogenes." (PMID 28936238, 2015). "In vaccine trials with the synthetic tumor peptide MART1 (melanoma-associated antigen recognized by T cells 1) (Melan-A) and with the NY-ESO-1 peptide antigen, addition of CpG ODN enhances antigen-specific CD8+ T cell responses." (PMID 26344622, 2014). "Xenografts morphologically mimicked the primary tumor and expressed S-100 protein and antigens associated with melanin synthesis (Melan-A, HMB45)." (PMID 24946937, 2014). "However, some patients experienced a loss of Melan-A antigen expression in tumor cells, underscoring the necessity for multiple antigen peptides to effectively suppress or eliminate tumor growth." (PMID 39840069, 2024). "However, in melanoma, increased CD163+ tumor-infiltrating macrophages (M2 phenotype) lead to the loss of Melan-A expression, causing pronounced invasive tumor phenotype." (PMID 39769450, 2024). "Indeed, due to its high mutational load as well as the presence of tumor-associated antigens (as gp100, tyrosinase, and Melan-A) that can elicit immune system activation, SKCM is considered one of the best targets in the field of anti-tumor immunotherapy." (PMID 35725560, 2022). "In samples collected one-week post-treatment initiation, there was a significant upregulation of caspase-3 in tumor cells with a loss of Melan-A staining; whether this is a form of immunogenic cell death is inconclusive." (PMID 32455916, 2020). "Tumour markers like TA-90 IC, Melan A, HMB-45, S-100 add to diagnostic accuracy." (PMID 17346341, 2007). "Indeed, the microarray analysis of the libraries indicated the presence of high copy numbers of well-known tumor associated antigens such as Melan-A but also of abundant tumor-related antigens scarcely targeted in immunotherapy." (PMID 16115316, 2005). "Histological assessment typically demonstrates tumor cells featuring prominent nucleoli and melanin granules, while immunohistochemical staining is positive for S100, Melan-A, and SOX10." (PMID 41142597, 2025). "The tumor origin was confirmed by one study through the evaluation of markers of adrenal cortical differentiation, as steroidogenic factor 1 (SF-1), melan-A and alpha-inhibin." (PMID 39890749, 2025). "Taken together, our results indicate that MCs exert a significant effect on Melan-A+ cells through juxtacrine and paracrine mechanisms already at the early stages of neoplastic lesion formation, as well as during tumor invasion into the dermis." (PMID 41373472, 2025). "Particularly noteworthy is the inverse relationship between the number of MCs and the number of Melan-A+ cells within the tumor itself: an increase in one population was accompanied by a decrease in the other." (PMID 41373472, 2025). "The aim of this study is to spatially phenotype and map the interactions of tryptase-positive mast cells in the tumor microenvironment with atypical Melan-A+ cells." (PMID 41373472, 2025). "Immunostaining of the tumor cells was positive for S-100, Melan A, HMB-45, and SOX10, consistent with MM." (PMID 41001300, 2025). "Among these, clusters 0, 1, 2, 3, and 7 are tumor cells that highly express MLANA, MITF, SOX10, and MKI67." (PMID 40356756, 2025). "For this purpose, we focused on a model antigen, namely the heteroclitic HLA-A2–restricted tumor-associated epitope ELAGIGILTV (ELA, Melan-A/MART-126–35)." (PMID 39847442, 2025).
tumor (continued). "We have performed differential mRNA expression analysis of NY-ESO-1, FNDC3B, and MLANA, which are the most common antigens among the tumor-specific groups." (PMID 38488909, 2024). "The current biopsy from the proximal palm demonstrated a cytologically similar tumor with extensive perineural spread and notable positivity for Melan-A." (PMID 38854338, 2024). "We also noted PD-L1 expression in CD163− MART1/Melan A− cells that are likely to indicate the expression by other tumour-infiltrating myeloid cell types." (PMID 38903497, 2024). "The significance of immunohistochemical markers such as CD31, CD34, Melan-A, and D2-40, provide unique insights into the tumor’s biological behavior and prognosis." (PMID 39399171, 2024). "Comparative in vitro experiments demonstrated that Treg-mediated suppression is more prominent in T cells expressing self-antigenic tumor cells (Melan-A) than in those expressing neoantigens (cytomegalovirus), specifically targeting CD8+ T cells." (PMID 39273452, 2024). "The marker genes S100B, PMEL, and MLANA showed significantly high expression in tumor cells in the SKCM_GSE115978_aPD1 dataset." (PMID 38911384, 2024). "The percentage of PD-L1-positive cells in Melan-A-positive tumor cells was significantly decreased in the GANT61-treated group as indicated by the LI (34 ± 2.23%) compared to the control group’s LI (72 ± 2.42%) (p < 0.05)." (PMID 37240209, 2023). "The number of Melan-A-positive tumor cells per mm2 in the GANT61-treated group was significantly suppressed compared to that in the DMSO-treated control group (p < 0.05)." (PMID 37240209, 2023). "In melanoma patients, exosomes found in ascites contained antigen-presenting molecules, as well as many tumour antigens like Melan-A/MART-1, TYRP or gp100, and were able to induce CTLs specific to Melan-A/MART-1 expansion through antigen deliver to DCs." (PMID 37022605, 2023). "Histopathological examination of the tumor revealed focal immunoreactivity for Melan-A, HMB-45, desmin, and CD117." (PMID 37041531, 2023). "Melan-A immunochemistry was performed to identify tumor cells, except when the Cellsearch device was used (automated identification)." (PMID 37446253, 2023). "In this study, we revealed an enhanced activation of both gp100- and Melan-A-specific T cells as well as more efficient tumor cell killing following RSK inhibitor pre-treatment." (PMID 37464364, 2023). "ACC tumor constructs showed expression of biomarkers associated with ACC, including SF-1, Melan A, and inhibin α." (PMID 37726363, 2023). "In contrast, Melan-A-positive tumor cells in the GANT61-treated group were confined to a portion of the bone marrow cavity and were not in contact with the lateral cortical bone." (PMID 37240209, 2023). "Immunohistochemically, the tumor cells were positive for CK, calretinin, D2-40, WT-1, and vimentin, and negative for Paird box 8, synaptophysin, chromogranin-A, inhibin-α, S-100, Melan-A, HMB45, and CD34." (PMID 38115250, 2023). "In the DMSO-treated group, Melan-A-positive tumor cells filled the bone marrow cavity and spread outward from the cortical bone destruction site." (PMID 37240209, 2023). "Although Melan-A peptide loading restored anti-tumor immunity, reinstatement of the native antigenic repertoire was more challenging as the de-differentiated phenotype was not reversible in culture." (PMID 36934113, 2023). "Immunohistochemical profiles (inhibin-a+, melan-A+, Syn+) indicated that the tumor had an adrenocortical origin." (PMID 36874125, 2023). "The percentage of SHH-positive cells in Melan-A-positive tumor cells was significantly decreased in the GANT61-treated group (LI: 45 ± 5.08%) compared to the control group (LI: 65 ± 2.63%) (p < 0.05)." (PMID 37240209, 2023). "Immunohistochemistry demonstrated partial, patchy desmin staining and weak heterogonous neuron-specific enolase immunoreactivity of tumor cells, but a focal staining for Melan-A." (PMID 35501497, 2023).
tumor (continued). "The patient underwent surgical excision of the tumor, and the positive immunohistochemical staining for human melanoma black 45 and Melan A made the definitive diagnosis." (PMID 37846416, 2023). "Circulating melan-A/MART-1 reactive T cells had a greater capacity for IFN-γ production while tumour-infiltrating cells produced more CXCL13 and displayed higher expression of co-inhibitory molecules." (PMID 37520560, 2023). "After 7 days of 3D NCI-H295R tumor construct culture, we observed expression of SF-1, Melan-A and, inhibin α are expressed as in 2D culture." (PMID 37726363, 2023). "We succeeded in isolating dozens of natural tumor-primed, Melan-A/MART-1-specific T cell clones derived directly from TILNs of cancer patients." (PMID 36032094, 2022). "While many tumor cells had strong nuclear staining of estrogen receptor (ER) and progesterone receptors (PR), some scattered tumor cells were positive for Melan-A in the cytoplasm." (PMID 36522714, 2022). "On the immunohistochemical (IHC) study, the tumor cells were strongly positive for Melan A and Vimentin." (PMID 34307221, 2021). "Melanoma antigen recognized by T-cells (MART1/Melan-A) is among the first characterized tumor antigens in melanoma cells." (PMID 33918733, 2021). "Nuclear SOX10 (n = 60/61) or cytoplasmic MLANA (n = 60/61) expression was detected in nearly all tumour cores, as expected." (PMID 33918976, 2021). "The tumour is also positive for markers expressed by other tumour types, such as melan A and calretinin." (PMID 33578929, 2021). "Collectively these observations indicate that MITF can be induced in response to irradiation, with increased MLANA antigen expression correlating with the irradiation-induced immune response that prevented tumor formation in mice." (PMID 33789714, 2021). "The examined tumor tissues were characterized by a high frequency of positive Melan-A (96.0%), HMB45 (94.0%), and S100 (92.0%)." (PMID 34639089, 2021). "Although tumor-infiltrating lymphocytes (TILs), infiltrate sites when they react to the melanoma antigen Melan-A/MART1, they are often functionally exhausted." (PMID 34944867, 2021). "Here, we designed a nanoparticle-based vaccine able to target human CD141+ (BDCA3+) DCs - the equivalent of murine CD8α+ DCs – and deliver both tumor Ag (Melan A) and α-GalCer." (PMID 32973811, 2020). "Tumor cells were positive for MART-1 (melan-A) staining, whereas pankeratin, CD56, synaptophysin, chromogranin, CDX2, p63, and PSA staining was negative." (PMID 32724562, 2020). "Microscopically, most of the tumours were composed of spindle cells with varying pigmentation, and both melan A and S100 were expressed by all of the tumours by immunohistochemistry." (PMID 32652526, 2020). "Here, using a nanovaccine loaded with the tumor Ag Melan A and α-GalCer and decorated with anti-CLEC9A Abs, we aimed to analyze the immune response in HIS-CD8/NKT mice." (PMID 32973811, 2020). "The tumor burden in the lungs was quantified using qRT-PCR, based on Melan-A and Pmel, which are two melanocyte-specific markers with zero basal expression in mock-treated lungs." (PMID 32625207, 2020). "Immunohistochemical studies showed a strong and diffuse expression of HMB-45 and Melan A within the tumor cells." (PMID 31171030, 2019). "CD4+ and CD8+ T cells accumulated around the margin of the overt SOX10+ Melan A+ ITM but were largely excluded from the tumor centre." (PMID 31885869, 2019). "Immunohistochemical studies showed the expression rate of HMB-45 and Melan A was 100% (22/22) and 86.4% (19/22) within the tumor cells." (PMID 31171030, 2019). "Immunohistochemistry showed strong positivity within tumor cells for Vimentin and Melan-A, weak but diffusely positive for TFE3 protein, while HMB45 was negative." (PMID 30876389, 2019). "The PEComa-like tumor showed strong Melan-A and weak transcription factor E3 (TFE3) protein expression but no TFE3 gene rearrangement." (PMID 30876389, 2019).